IGF1 (insulin like growth factor 1)
Diseases named in the same sentence as IGF1 in open-access papers (continued):
Sharing a sentence is not in itself a finding about the gene and the disease.
Insulin resistance (continued). "IGF-1 can decrease blood glucose levels and improve the condition of insulin resistance, and it is regarded as a promising drug for treating T2DM." (PMID 32024487, 2020). "Exercise can reduce insulin levels and insulin resistance, thereby decreasing fasting glucose, total IGF-1, and increasing IGF binding proteins." (PMID 33108715, 2020). "Collectively, obesity-induced insulin resistance enhances IGF-1 activity in concert with the excess estrogen locally produced in obese women, leading to development of EC." (PMID 32842547, 2020). "Many studies supporting that hyperglycemia, insulin resistance, hyperinsulinemia, IGF-1 levels, dyslipidemia, inflammatory, and cytokines affect tumor cell microenvironment and intracellular signal transduction and help tumor growth and progression." (PMID 33134394, 2020). "IGF-1 administration has been shown to reduce the serum glucose levels not only in healthy individuals, but also in those with insulin resistance, type I diabetes, and T2DM, and it is regarded as a promising drug for the treatment of diabetes." (PMID 32024487, 2020). "In conclusion, increasing IGF-1 levels was beneficial for body composition but detrimental with respect to insulin resistance." (PMID 33633687, 2020). "In terms of metabolism, the aging process is characterized by changes in body composition and insulin resistance with declines in the production of growth hormone, insulin-like growth factor-1, and sex steroids." (PMID 33014521, 2020). "In consideration of the ever-growing prevalence of obesity and insulin resistance, an increasing interest to the development of new experimental antineoplastic drugs—targeting IGF-1 and/or insulin signaling pathways—are being employed in clinical trials." (PMID 32351453, 2020). "Increased insulin resistance during and before puberty is partly due to increased body fat content but also to elevated serum levels of IGF-1, which is primarily regulated by growth hormone." (PMID 32816094, 2020). "The associations of genetically predicted IGF-1 levels with type 2 diabetes and coronary artery disease were similar after adjustment for insulin levels or insulin resistance, whereas adjustment for height resulted in somewhat stronger associations." (PMID 32548700, 2020). "It has also been demonstrated that low IGF-1 levels correlate with insulin resistance, atherogenic dyslipidemia, and increased blood pressure that constitute the three pillars of metabolic syndrome." (PMID 32655494, 2020). "The interaction between IGF-1, central obesity and insulin resistance is difficult to dissect precisely in clinical studies but is certainly playing a major role in OSA-related cardio metabolic co-morbidities." (PMID 32655494, 2020). "The most clear finding was that increasing the GH dose to a high-normal IGF-1 level led to a significant increase in insulin resistance, but a reduction in waist circumference." (PMID 33633687, 2020). "In parallel to the favorable effect of increasing the IGF-1 level on waist circumference compared to decreasing the IGF-1 level (p=0.05), there was a significant difference in the effect on insulin resistance (p=0.03)." (PMID 33633687, 2020). "Causes of cancer risks in diabetic patients involved hyperglycemia, hyperinsulinemia, insulin resistance, distorted insulin-like growth factor-1 (IGF-1) pathway, oxidative stress, enhanced inflammatory processes and aberrant sex hormone production." (PMID 33096896, 2020). "Insulin resistance, a hallmark of T2DM, results in hyperinsulinemia eliciting elevated insulin-like growth factor 1 (IGF1) levels which promote cell growth and proliferation of mucosa cells in the large intestine." (PMID 32971867, 2020). "Previous studies found that a low circulating IGF-1 level was independently related to insulin resistance and hyperglycaemia, while a normal to high circulating IGF-1 level independently led to a reduced prevalence of MetS." (PMID 32391265, 2020).
Insulin resistance (continued). "Patients with a deletion in the IGF-1 gene have been shown to develop insulin resistance that improved with IGF-1 therapy." (PMID 30744635, 2019). "A few intervention studies on breast cancer survivors showed that a healthy diet and exercise modified the levels of IGF-1 and insulin resistance-related markers." (PMID 31816813, 2019). "This is a rather unfavorable phenomenon because IGF-1 can promote muscle lipids and glucose metabolism and reduce insulin resistance." (PMID 31252598, 2019). "Insulin resistance and hyperinsulinemia are known to increase the expression of insulin and insulin-like growth factor-1 (IGF-1)." (PMID 31867441, 2019). "This mouse model replicated diabetes and insulin resistance in people by exhibiting elevated IGF-1 and insulin levels, insulin resistance, and enhanced intimal hyperplasia when they are fed HFD vs. control." (PMID 31562314, 2019). "The most important mechanism is currently believed to be insulin resistance related to GH/IGF-1 excess." (PMID 31736874, 2019). "Insulin resistance-induced hyperinsulinemia and IGF-1 can further enhance the biological effects of TNF-α by activating the TNF-α signaling pathway." (PMID 31440472, 2019). "Insulin resistance and altered insulin-like growth factor-1 (IGF-1) pathway activation, changes in bioavailability of sex hormones and a chronic inflammatory state related to obesity conditions have been recognized to induce cancer development and progression." (PMID 31052147, 2019). "The mechanism of insulin resistance in AD is also related to insulin-like growth factor 1 (IGF-1) resistance, and insulin receptor substrate 1 (IRS-1) disability, probably triggered by Aβ oligomers." (PMID 31428627, 2019). "IGF1 therapy has also been proved to revert insulin resistance, reduce cholesterol and triglycerides levels, and significantly increase FFA concentrations." (PMID 29702590, 2018). "Experimental evidence indicated that insulin resistance and hyperinsulinemia increased the expression of insulin and insulin-like growth factor-1 (IGF-1)." (PMID 30228976, 2018). "These include insulin resistance (IR), insulin growth factor-1 (IGF-1), adipocytokines, thyroid stimulating hormone (TSH), and estrogens." (PMID 29805933, 2018). "The insulin resistance of puberty, which was found to be directly correlated with IGF-1 levels, leads to compensatory hyperinsulinemia which serves to amplify the anabolic effect of insulin during this period of rapid growth." (PMID 29942285, 2018). "IGF1 is necessary for normal insulin sensitivity, and impairment of IGF1 synthesis results in a worsening state of insulin resistance." (PMID 29702590, 2018). "In acromegaly, HSI is mainly related with insulin resistance and the reduction of GH and IGF-1 levels, and above all the improvement in insulin sensitivity leads to an improvement of this surrogate index of hepatic steatosis." (PMID 30662461, 2018). "Zn deficiency is likely to evoke insulin resistance in such patients by way of almost the same mechanism as chronic HCV infection, including hyperferritinemia and/or lower circulating free IGF-1 levels." (PMID 29342898, 2018). "Further investigation of other factors affecting IGFBP-1 interactions and insulin resistance is required, in this case, IGF-1." (PMID 30775682, 2018). "Here, we describe briefly the IGF-1 and adiponectin systems, and we then focus on their putative interplay in relation to several pathological conditions, including obesity, diabetes, insulin resistance, cardiovascular disease, and cancer." (PMID 29036907, 2017). "Hepatic insulin growth factor 1 (IGF-1) modulates insulin sensitivity, thus decreased IGF-1 levels are linked to insulin resistance." (PMID 29085333, 2017). "After adjusting for age gender and BMI, fasting glucagon levels were positively correlated with 2-h post-load glucose levels, the HOMA index of insulin resistance and fasting insulin levels, and were negatively correlated with IGF-1 levels." (PMID 28881681, 2017).
Insulin resistance (continued). "To reach this goal, we provide a concise description of both IGF-1 and adiponectin systems, and we focus on the putative relationship of the two hormones in obesity, diabetes, insulin resistance, heart failure, and cancer." (PMID 29036907, 2017). "Factors that influence the aging process include insulin resistance (IR), growth hormone (GH) activity, insulin-like growth factor-1 (IGF-1), and leukocyte telomere length (LTL)." (PMID 29375617, 2017). "In another clinical study, IGF-1 combined with IGFBP-3 has been shown to improve insulin sensitivity and to reduce complications associated with insulin resistance in HIV/AIDS patients on antiretroviral therapy." (PMID 29422987, 2017). "Knockdown of Igf-1 from postnatal murine liver accounted for 75% reduction in circulating IGF-1 levels accompanied by a fourfold increase in GH, which can lead to insulin resistance." (PMID 28298931, 2017). "The signaling interplay between IGF-1 and adiponectin in relation to insulin resistance is a very complex matter, above all when an abnormal GH secretion is taken into account." (PMID 29036907, 2017). "Insulin resistance is a well-known feature of obesity, and a low plasma IGF-1 concentration has been reported to be significantly associated with insulin sensitivity." (PMID 27138941, 2016). "Insulin resistance, hyperinsulinemia, elevated levels of IGF-1, inflammation, increased sex hormones bioavailability and hyperglycemia are considered to be responsible for increased cancer risk in obese individuals." (PMID 27724912, 2016). "This type of obesity is correlated with insulin resistance, increased level of insulin-like growth factor (IGF)-1, and fatty acids." (PMID 26951106, 2016). "Central obesity is an independent predictor of insulin resistance and higher levels of free insulin-like growth factor-1 (IGF-1) compared with general obesity." (PMID 27247890, 2016). "This combination of lowered serum IGF-1 and increased GH secretion leads to increased insulin resistance—as in the systemic deletion but also developed glucose intolerance." (PMID 26733412, 2016). "Epidemiologic data suggest that insulin resistance with hyperinsulinaemia, as well as increased insulin and insulin-like growth factor-1 (IGF-1) signalling account for the relationship between these conditions." (PMID 27795741, 2016). "Several other studies (one of them being a large scale community-based Framingham Heart Study) have suggested a role for IGF-1 in the prevalence of insulin resistance and MetS." (PMID 26733412, 2016). "Another potential link between obesity and HCC is hyperinsulinemia resulting from insulin resistance, which exerts growth effects either directly or via release of insulin-like growth factor-1 (IGF-1)." (PMID 30873458, 2016). "It is known that insulin resistance, hyperinsulinaemia and elevated levels of IGF-1 promote tumor cell growth." (PMID 27760202, 2016). "An interesting experiment shows how, in the presence of insulin resistance, there is up-regulation of the insulin/IGF-1 hybrid receptor expression in both, muscle and fat." (PMID 26733412, 2016). "In pathophysiological states, including increased insulin resistance, the hybrid receptor number is changed significantly, thus potentially abrogating the chance for IGF-1 to alter glucose metabolism." (PMID 26733412, 2016). "This process is metabolically characterized by insulin resistance, changes in body composition, and physiological declines in sex steroids, growth hormone (GH) and insulin-like growth factor-1 (IGF-1)." (PMID 26840281, 2016). "H3M e3K36 is sensitive to the prenatal environment’s glucose level with resultant alteration of IGF-1 mRNA expression and ultimately vulnerability to adult-onset insulin resistance." (PMID 26787358, 2016).
Insulin resistance (continued). "In a similar study, the pivotal role for the IGF-1 in insulin sensitivity has received further support from liver-specific IGF-1 KO mice which exhibited overt insulin resistance and hyperinsulinaemia that was reversed by the administration of IGF-1." (PMID 26733412, 2016). "Here we found reductions in plasma insulin and IGF-1 following CR, strongly impacted on fasting glucose, with insulin also influencing insulin sensitivity and insulin resistance." (PMID 26061745, 2015). "Hyperinsulinemia—consequence of insulin resistance—increases the bioavailability of insulin-like growth factor (IGF)-1 by inhibiting liver production of IGF-binding proteins." (PMID 26030767, 2015). "With increasing insulin resistance, in overt T2DM, the IGFBP1 level increased, which caused a significant decrease in free IGF-1 concentration." (PMID 28031898, 2015). "On the other hand Ser636/639 phosphorylation is strongly induced by IGF-1 in both aged WT and Ames fibroblasts which is a characteristic of insulin resistance." (PMID 26474286, 2015). "The deregulation of the brain insulin/IGF-1 signaling pathways influences energy metabolism and insulin resistance, and results in triggering pathological changes in the nervous and neuroendocrine systems." (PMID 28031898, 2015). "On the other hand, an inverse relationship between IGF-1 circulating levels and incidence of metabolic syndrome (MetS) with liver steatosis, insulin resistance, hyperlipidemia and visceral obesity has been identified." (PMID 26467524, 2015). "This would suggest an effect of previous exposure to elevated levels of IGF-1 as well as persistent exposure during treatment in the development of insulin resistance and diabetes." (PMID 25996963, 2015). "For the first time, this study demonstrated that insulin resistance appears to be part of the physiopathologic significance of decreased IGF-1 levels in HCC progression." (PMID 24586785, 2014). "Insulin resistance is thus associated with reduced responses to insulin signaling in the IR/IRS-1/PI3K and greatly with IGF1 in the IGF1R/IRS-2/PI3K signaling pathways." (PMID 25346723, 2014). "A significant inverse association was found between IGF-1 and insulin levels, as well as between IGF-1 levels and insulin resistance index (HOMA-IR)." (PMID 24586785, 2014). "Insulin resistance appears to be a part of the physiopathologic significance of decreased IGF-1 levels in HCC progression." (PMID 24586785, 2014). "Other studies have reported positive associations of irisin with nutritional markers such as BMI, fat mass, IGF-1 and insulin, and with markers of the metabolic syndrome such as higher blood pressure, insulin resistance and lipid levels." (PMID 24926783, 2014). "These diet-related metabolic disorders are multifaceted but characterized by peripheral insulin resistance, compensatory overproduction of insulin and increased bioavailability of insulin-like growth factor-1 (IGF-1)." (PMID 25295009, 2014). "In our data, we see that insulin resistance exists in both overweight and obese adolescents, in spite of the levels of IGF-1 increasing in the overweight and obese individuals." (PMID 23383064, 2013). "Insulin resistance induces muscle wasting through complex mechanisms, including insulin/IGF-1 and PI3K/Akt signaling pathways." (PMID 24382946, 2013). "We determined levels of insulin and adiponectin as markers of insulin resistance, and of IGF-1 as a hormone sensitive to the diet." (PMID 23451233, 2013). "The key role is most probably played by hyperinsulinemia and insulin resistance as well as an increase of bioactive IGF-1." (PMID 24369529, 2013). "Liver-specific IGF-1 knockout mice exhibit insulin-resistance and hyperinsulinemia that are reversed by recombinant insulin-like growth factor-1 (rhIGF-1) treatment." (PMID 24392014, 2013). "IGF-1 and insulin activate many of the same intracellular signaling pathways, and altered IGF-1 signaling has been demonstrated in states of insulin resistance." (PMID 24252636, 2013).
Insulin resistance (continued). "In obese patients, excessive insulin is secreted to inhibit hyperglycemia due to insulin resistance; however, insulin itself promotes the growth of cancer cells through stimulation of the activity of insulin-like growth factor-1 (IGF-1)." (PMID 23291663, 2013). "DOL 21 was chosen for our epigenetic profile evaluation of the IGF-1 gene because it precedes the confounders of adolescence, weight gain, and insulin resistance." (PMID 22548154, 2012). "The relationship between type 2 diabetes and cancer is complex, possibly involving insulin resistance, hyperinsulinemia, and elevated levels of insulin-like growth factor-1 (IGF-1) in tumor cell growth." (PMID 22719752, 2012). "But Klotho induces IGF-1 and insulin resistance, whereas dwarf mice with reduced IGF-1 and insulin levels have enhanced insulin sensitivity." (PMID 22683661, 2012). "Obese patients also have higher levels of circulating free IGF-1 and serum insulin, and a reduction of obesity remains a potential target of decreasing insulin, IGF-1, and insulin resistance." (PMID 23050155, 2012). "Experimental data show IGF-1's protective effects against systemic inflammation, insulin resistance, and free fatty acid production, all of which are consequences of obesity." (PMID 22438892, 2012). "Most studies but not all of them suggest that the relationship between adiponectin and cancer is correlated with hormones, including estrogen, IGF1, obesity, and insulin resistance." (PMID 23213569, 2012). "By contrast, higher ROS levels inhibit IGF-1 signaling cascades and recent evidence implicates ROS as downregulators of IGF-1 signaling and inducers of insulin resistance and its pathological sequelae." (PMID 22175016, 2012). "IGF-1 is ubiquitously distributed in various tissues and cells, and it plays an important role for prevention of insulin resistance and protection against age-related oxidative damage, leading to β-cell apoptosis." (PMID 22194889, 2011). "IGF-1 deficiency mice were very insulin insensitive, while administration of IGF-1 shows the insulin resistance improvement." (PMID 21689475, 2011). "Metformin decreases insulin resistance and indirectly reduces levels of insulin and IGF-1, which promote cancer cell proliferation." (PMID 24212624, 2011). "When the soluble Klotho protein was intraperitoneally administered to wild-type mice, the insulin and IGF-1 sensitivity of the mice was impaired, indicating that increased Klotho protein in the blood induced insulin resistance, as well as IGF-1 resistance." (PMID 21876806, 2011). "The GH and IGF1 system have complex feedback mechanisms that, in general, promote insulin resistance." (PMID 21070590, 2011). "Blood glucose, thyroid function, HbA1c, and IGF-1 should be monitored once a year except in cases exhibiting clear clinical evidence of insulin resistance or an HbA1C of 6% at the beginning of treatment." (PMID 21771322, 2011). "The objective is to investigate the role of insulin resistance/sensitivity in carcinogenesis by studying the relation between insulin resistance/sensitivity and IGF-1 levels in cancer patients." (PMID 17953765, 2007). "Well controlled studies in humans are essential to study the link between insulin resistance, hyperinsulinaemia, IGF-1 and carcinogenesis." (PMID 17953765, 2007). "This is done by studying the relation between insulin resistance/sensitivity and IGF-1 levels in cancer patients." (PMID 17953765, 2007). "Physical activity may also contribute to restoring hormonal balance by reducing insulin resistance and hyperinsulinemia, as insulin and insulin-like growth factor 1 (IGF-1) indirectly stimulate oestrogen production." (PMID 41515258, 2026). "Disruption of IGF-1 signaling, as seen in states resembling insulin resistance, may therefore worsen glutamate-driven excitotoxicity and contribute to adverse outcomes." (PMID 41993473, 2026).